RN7SL466P (RNA, 7SL, cytoplasmic 466, pseudogene)
Gene: Miscellaneous RNA gene on chromosome 1 (161,735,808 to 161,736,102, forward strand). Ensembl gene ENSG00000241347.
Homologues: Orthologues: chimpanzee Metazoa_SRP (99% identical), macaque Metazoa_SRP (88% identical). Paralogues in human: RN7SL2 (81% identical), RN7SL1 (81% identical), RN7SL3 (80% identical), RN7SL47P (78% identical), RN7SL575P (78% identical), RN7SL408P (78% identical), RN7SL44P (78% identical), RN7SL664P (78% identical), RN7SL11P (77% identical), RN7SL383P (77% identical), RN7SL769P (77% identical), RN7SL15P (77% identical), and 705 more.